VPS13D (vacuolar protein sorting 13 homolog D)
Description:
Mediates the transfer of lipids between membranes at organelle contact sites (By similarity). Functions in promoting mitochondrial clearance by mitochondrial autophagy (mitophagy), also possibly by positively regulating mitochondrial fission. Mitophagy plays an important role in regulating cell health and mitochondrial size and homeostasis.
Synonyms: KIAA0453; FLJ10619; BLTP5D; SCA24; SCAR4; SCASI
Tractability: PROTAC: ubiquitination databases record sites on it; its protein half-life has been measured.
Gene: Protein-coding gene on chromosome 1 (12,230,030 to 12,512,047, forward strand). Ensembl gene ENSG00000048707.
Subcellular location (Human Protein Atlas): Nucleoplasm; Vesicles; Cytosol
Gene Ontology:
Molecular function: phospholipid transfer activity
Biological process: mitochondrion organization; positive regulation of mitophagy; intermembrane lipid transfer; macroautophagy; phospholipid transport
Cellular component: extracellular exosome; mitochondrion; endosome membrane; mitochondrial outer membrane
Genetic constraint (gnomAD): Loss-of-function variants: 173 observed, 460.73 expected, observed/expected ratio (o/e) 0.38, 90% interval 0.33 to 0.43. The upper end of that interval is the gene's LOEUF score, 0.43, which puts it in group 1 of 6, group 1 being the genes least tolerant of losing a copy. Missense variants: 4,663 observed, 5,588.3 expected, observed/expected ratio (o/e) 0.83, 90% interval 0.81 to 0.86. Synonymous variants: 1,938 observed, 2,077.2 expected, observed/expected ratio (o/e) 0.93, 90% interval 0.9 to 0.97.
Gene-disease validity (ClinGen):
ClinGen rates the evidence that VPS13D causes each of these diseases.
Leigh syndrome (autosomal recessive): Limited. A progressive neurological disease defined by specific neuropathological features associating brainstem and basal ganglia lesions.
Homologues: Orthologues: chimpanzee VPS13D (99% identical), macaque VPS13D (99% identical), pig VPS13D (94% identical), mouse Vps13d (93% identical), rat Vps13d (93% identical), rabbit VPS13D (91% identical), guinea pig VPS13D (90% identical), tropical clawed frog vps13d (74% identical), zebrafish vps13d (60% identical), Drosophila melanogaster Vps13D (29% identical), Caenorhabditis elegans C25H3.11 (13% identical). Paralogues in human: VPS13C (17% identical), VPS13A (14% identical).
Diseases named in the same sentence as VPS13D in open-access papers:
VPS13D is named in the same sentence as 43 diseases in open-access papers, as found by Europe PMC text mining. Sharing a sentence is not in itself a finding about the gene and the disease. The quoted sentences say what the papers report.
Ataxia (12 papers, 2020 to 2025). Ataxia refers to impaired coordination of voluntary muscle movement. "VPS13D variants induce heterogeneous neurodegenerative disorders such as ataxia, developmental delay, spastic paraplegia, or spinocerebellar ataxia." (PMID 35720097, 2022). "VPS13D mutations cause a recessive ataxia-spasticity spectrum movement disorder but have also been reported to cause a pure or complicated form of HSP." (PMID 33646413, 2021). "Meanwhile, the patient with a compound heterozygous mutation (p.Ser405Arg/p.Arg3141Ter) in the VPS13D showed a childhood onset complicated form of HSP associated with cerebellar ataxia, cervical dystonia, cataracts, and chorioretinal dystrophy." (PMID 31876103, 2020). "It is worth noting that rare cases of LS may be attributed to genes not directly implicated in OXPHOS function, such as those associated with VPS13D-related ataxia phenotypes, serving as a notable illustration of LS phenocopy." (PMID 38791166, 2024). "With this optimized tool, we have created a model to investigate the progressive neurological and locomotor defects associated with Vps13D perturbation in fly neurons, better modeling the clinical ataxia phenotype described in patients with mutations in VPS13D." (PMID 37457002, 2023). "Rare cases of LS could be caused by genes not directly involved in OXPHOS function—MORC2-associated SMA-like phenotypes and VPS13D-associated ataxia + phenotypes are a bright illustration of LS phenocopy." (PMID 36675121, 2023). "Indeed, loss of Vps13D function in many different cell types leads to severely enlarged mitochondria, including Drosophila intestinal cells, HeLa cells, and cultured fibroblasts from human ataxia patients containing point mutations in the VPS13D gene." (PMID 34383748, 2021). "Mutations in Vps13D, required for mitochondrial size and clearance, are also causative for recessive spastic paraplegia or ataxia, thus suggesting that lipid transfer to or from the ER might be vulnerable in HSP, although the exact subcellular compartments where Vps13D acts are still unknown." (PMID 32116502, 2020).
spastic ataxia (5 papers, 2020 to 2023). "VPS13D is a rare disease gene, with mutations in VPS13D being associated with pediatric and young adult spastic ataxia or spastic paraplegia." (PMID 34459017, 2021). "Recently, VPS13D mutations were identified as a cause of VPS13D‐related movement disorders, which show several phenotypes including chorea, dystonia, spastic ataxia, and spastic paraplegia." (PMID 31876103, 2020). "We confirmed herein that spastic ataxia may be related to VPS13D pathogenic variants and we showed abnormal mitochondrial morphology and reduced mitochondrial OXPHOS complexes in skin fibroblasts suggesting altered mitochondrial function." (PMID 35151251, 2022). "Here, we demonstrate that vacuolar protein sorting-associated protein 13D (VPS13D), loss-of-function mutations of which cause spastic ataxia, coordinates FA trafficking in conjunction with the endosomal sorting complex required for transport (ESCRT) protein tumor susceptibility 101 (TSG101)." (PMID 33623047, 2021). "Recently, VPS13D pathogenic variants have been successively reported in patients displaying variable neurological phenotypes generally dominated by movement disorders including chorea, dystonia, tremor, ataxia, spastic paraplegia, spastic ataxia and seizures with highly variable age at onset." (PMID 35151251, 2022).
Cohen syndrome (3 papers, 2020 to 2023). Cohen syndrome (CS) is a rare genetic developmental disorder characterized by microcephaly, characteristic facial features, hypotonia, non-progressive intellectual deficit, myopia and retinal dystrophy, neutropenia and truncal obesity. "Meanwhile, retinal dystrophy is a major symptom of Cohen syndrome caused by VPS13B mutations in the VPS13 family, and thus VPS13D mutations might cause the retinal symptom." (PMID 31876103, 2020). "Furthermore, multiple inward‐facing missense mutations were found within the hydrophobic interior of the RBG domain, one of which was pathogenic for Cohen syndrome in VPS13B (p.Ile1636Asn, VCV000977843.1), and another one was likely pathogenic in VPS13D (p.Ile1170Ser, VCV000806071.11)." (PMID 36404287, 2023).
hereditary spastic paraplegia (2 papers, 2022 to 2023). Hereditary spastic paraplegias (HSP) comprise a genetically and clinically heterogeneous group of neurodegenerative disorders characterized by progressive spasticity and hyperreflexia of the lower limbs. "Mutations in each of the four members can cause movement disorders, among which VPS13D deficiency causes either autosomal recessive spinocerebellar ataxia-4 (SCAR4), or hereditary spastic paraplegia (HSP), both are characterized by cerebellar ataxia." (PMID 35420383, 2022).
Adult onset (1 paper, 2023). Onset of disease manifestations in adulthood, defined here as at the age of 16 years or later. "Mutations in the human gene VPS13D cause the adult-onset neurodegenerative disease ataxia." (PMID 37457002, 2023).
breast carcinoma (1 paper, 2021). "Furthermore, the COSMIC database v94 revealed the mutation incidence in liver, skin, and breast cancer to be 8.62, 8.61, and 4.54, respectively, suggesting a possibility that the mutations in Vps13d and/or Tnrc6b may be associated with the carcinogenesis demonstrated in the present study." (PMID 34912374, 2021).
chorea-acanthocytosis (1 paper, 2021). Chorea-acanthocytosis (ChAc) is a form of neuroacanthocytosis and is characterized clinically by a Huntington disease-like phenotype with progressive neurological symptoms including movement disorders, psychiatric manifestations and cognitive disturbances. "Humans express four different VPS13 paralogs, designated A through D. Mutations in VPS13A, VPS13B, VPS13C and VPS13D are associated with the neurodegenerative disorder Chorea-Acanthocytosis (ChAc), Cohen Syndrome, Parkinson’s Disease, and a form of cerebellar ataxia, respectively." (PMID 34201352, 2021).
epileptic seizures (1 paper, 2024). "Notably, a significant reduction in VPS13D expression was observed in the epileptic seizure model group compared with that in the control group (P < 0.05)." (PMID 39286655, 2024). "Building on our previous study, we propose the scientific hypothesis that VPS13D plays a crucial role in the occurrence of epileptic seizures." (PMID 39286655, 2024).
gastric cancer (1 paper, 2021). A primary or metastatic malignant neoplasm involving the stomach. "Survival analysis of subtype C2 shows that ABCA13, VPS13D, and CUBN affect the survival of gastric cancer." (PMID 34728653, 2021).
Kabuki syndrome (1 paper, 2025). Kabuki syndrome (KS) is a multiple congenital anomaly syndrome characterized by typical facial features, skeletal anomalies, mild to moderate intellectual disability and postnatal growth deficiency. "Whole-exome sequencing identified the KMT2D variant, along with compound heterozygous VPS13D variants, which explains the combined Kabuki syndrome and SCAR4 phenotype." (PMID 41155848, 2025).
Leigh syndrome (1 paper, 2024). "In two publications, patients with pathogenic variants in the VPS13D gene were assigned to Leigh syndrome (LS; OMIM #256000), a frequent mitochondrial pathology of childhood." (PMID 38791166, 2024). "The VPS13D gene, part of the VPS13 family, has emerged as a crucial player in neurological pathology, implicated in diverse phenotypes ranging from movement disorders to Leigh syndrome." (PMID 38791166, 2024).
Obesity (1 paper, 2023). Accumulation of substantial excess body fat. "We then ascertained which genes were altered in opposite directions in these nutritional extremes and found Calm2 to be increased in obesity but decreased in ABA while Vps13d was decreased during obesity yet increased during ABA." (PMID 37582711, 2023).
paraplegia (1 paper, 2022). Complete paralysis of the lower half of the body including both legs, often caused by damage to the spinal cord. "Recently, it has been found that ataxia/spastic paraplegia-associated isoform VPS13D is a key regulator of MERCS and VPS13D suppression leads to severe defects in mitochondrial morphology, mitochondrial cellular distribution, and mitochondrial DNA synthesis." (PMID 35625553, 2022).
spinocerebellar ataxia-4 (1 paper, 2025). "Here, we used CRISPR/Cas9 gene editing to create VPS13D-related spinocerebellar ataxia-4 missense mutations and C-terminal deletion in VPS13D's ortholog vps-13D in Caenorhabditis elegans." (PMID 39957248, 2025).
movement disorder (5 papers, 2020 to 2026). Neurological conditions resulting in abnormal voluntary or involuntary movement, which may impact the speed, fluency, quality and ease of movement. "Pathogenic variants in the VPS13D gene have been consistently reported in patients with variable neurological phenotypes, typically with a predominance of movement disorders." (PMID 38791166, 2024). "Pathogenic genetic variations within VPS13C and VPS13D genes have recently been identified in movement disorder phenotypes." (PMID 34046249, 2021). "Recently, VPS13D (OMIM *608877) was reported to be a cause of childhood onset movement disorders and recessive ataxia with spasticity." (PMID 31876103, 2020). "Vps13D, an evolutionarily conserved lipid transfer and ubiquitin binding protein, is required for mitochondrial clearance during Drosophila intestine development and has been implicated in a pediatric movement disorder." (PMID 41576035, 2026). "Two of the mammalian VPS13 isoforms, VPS13A and VPS13D, whose loss-of-function mutations cause Chorea Acanthocytosis and heterogeneous movement disorders including ataxias, respectively, act at contacts between the ER and mitochondria, although they bind to mitochondria via different mechanisms." (PMID 34046249, 2021). "Mutations in genes that are required for mitophagy, including Vps13D, PINK1, and Parkin, are associated with movement disorders, but gaps exist in our understanding of how Vps13D regulates mitophagy." (PMID 41576035, 2026). "Consistent with SCAR4 patient movement disorders and mitochondrial dysfunction, vps-13D mutant worms exhibit locomotion defects and abnormal mitochondrial morphology." (PMID 39957248, 2025). "Recent developments identified VPS13C and D as disease causing mutations in other movement disorders, namely mutations in VPS13C cause autosomal recessive Parkinsons disease/Lewy body disease and VPS13D mutations cause spinocerebeller ataxia with saccadic intrusions (SCAR4)." (PMID 34046249, 2021).
neurological diseases (5 papers, 2021 to 2025). "There are four members of the Vps13 family—Vps13a, Vps13b, Vps13c, and Vps13d—and mutations in each gene cause distinct neurological diseases." (PMID 39063018, 2024). "Our ability to dissect these causally related defects in the study of Vps13D should promote new inroads into understanding the pathophysiology of neurological disease." (PMID 34383748, 2021). "The development of this optimized system allows us to more precisely examine the degenerative phenotypes caused by Vps13D disruption, and can likely be utilized in the future for other genes associated with neurological diseases whose manipulation causes developmental lethality in Drosophila." (PMID 37457002, 2023). "Furthermore, the performed functional studies could be used as biomarker helping diagnosis of VPS13D-related neurological disorders when molecular results are uneasy to interpret." (PMID 35151251, 2022).
cancer (3 papers, 2021 to 2022). A tumor composed of atypical neoplastic, often pleomorphic cells that invade other tissues. "Although no clear associations between mutations in Vps13d and human cancer have been documented, VPS13D was found to play a dual role in mitochondrial morphology and peroxisome biogenesis in human cells." (PMID 34912374, 2021). "As for the other 2 mRNA, VPS13D and CELF3, some multi-omics or pathways based analysis indicated the their roles as potential drug target or biomarker for metastasis, but more experimental evidences are needed to further confirm their molecular roles in cancer biology." (PMID 35751033, 2022).
neurodegenerative disease (2 papers, 2021 to 2023). A disorder of the central nervous system characterized by gradual and progressive loss of neural tissue and neurologic function. "Our starting point was to understand the neuronal function of the neurodegenerative disease-associated protein Vps13D (Vacuolar Protein Sorting protein 13D)." (PMID 34383748, 2021).
tumor (2 papers, 2013 to 2024). "Among them, TAZ was up-regulated in tumor tissue compared with para-cancerous tissue, and the expression of the remaining eight genes (including SLC25A4, SLC25A5, PARK, PINK1, MFN2, HUWE1, VPS13D, and LRBA) was down-regulated in tumor tissue." (PMID 38373978, 2024).
adenocarcinoma (1 paper, 2021). A common cancer characterized by the presence of malignant glandular cells. "The mutations at Vps13d codon 295 and Tgfbr2 codon 549, found in the DMBA-treated organoid-derived adenocarcinomas were observed also in the passaged nodules, diagnosed as SCCs." (PMID 34912374, 2021). "Of note, SNVs shared between the DMBA-induced organoid-derived adenocarcinomas and 0.6 μM DMBA-treated organoids (prior to injection into the subcutis of nude mice) were limited to 10 genes, including Tnrc6b and Vps13d, which were selected by the IGV." (PMID 34912374, 2021).
mitochondrial disease (1 paper, 2023). "In this article, we present clinical and molecular findings of 219 patients with LS and give the detailed description of three cases with rare findings in nuclear genes MORC2, NARS2 and VPS13D, demonstrating wide genetic heterogeneity of this mitochondrial disease." (PMID 36675121, 2023).
VPS13D also shares sentences with these, for which no sentence is quoted: Spastic paraplegia (3 papers); acute myeloid leukemia (1); ataxia telangiectasia (1); cataract (1); cerebellar ataxia (1); cerebrotendinous xanthomatosis (1); cervical dystonia (1); Chorea (1); developmental delay (1); Dystonia (1); Friedreich ataxia (1); genetic disease (1); Leukoencephalopathy (1); mammary adenocarcinomas (1); mental retardation (1); microcephaly (1); muscular dystrophy (1); Parkinson disease (1); recessive spastic paraplegia (1); Retinal dystrophy (1); tumors of the ovary (1); viral infection (1).